KCNQ1 (potassium voltage-gated channel subfamily Q member 1)
Diseases named in the same sentence as KCNQ1 in open-access papers (continued):
Sharing a sentence is not in itself a finding about the gene and the disease.
long QT syndrome (continued). "Approximately 40–50% of all long QT syndrome patients carry a mutation in the IKs subunit, KCNQ1, which puts them at risk of potentially life-threatening arrhythmia." (PMID 31461851, 2019). "Clinically, more than 300 loss-of-function mutations in KCNQ1 have been found to induce functional defects to the IKs current, causing long QT syndrome (LQTS) that predisposes patients to life-threatening cardiac arrhythmia." (PMID 31329101, 2019). "Loss-of-function mutations in KCNQ1 can reduce IKs and underlie the inherited form of long QT syndrome (LQT1), while gain-of-function mutations in KCNQ1 can act to increase channel opening, resulting in enhanced IKs." (PMID 30967788, 2019). "Two unrelated patients (index cases 76 and 84) carried a variant (KCNQ1_p.K393N) that had previously been reported to be associated with long QT syndrome (CM078293), although via a different nucleotide change (cytosine, not a thymine)." (PMID 30020974, 2018). "We also found a spectrum of corrected QT intervals in the mutation carriers, which indicates incomplete penetrance and variable expressivity of the mutations in the heart, similarly as described for long QT syndrome due to loss-of-function KCNQ1 mutations." (PMID 29097701, 2017). "A study involving 14 patients diagnosed with KCNQ1 long QT syndrome showed increased postprandial insulin release in KCNQ1 mutation carriers compared with two control participants." (PMID 29259974, 2017). "Second, loss-of-function mutations in KCNQ1, as seen in patients with long QT syndrome, have been shown to cause hyperinsulinemia and subsequent hypoglycemia." (PMID 29259974, 2017). "Loss-of-function mutations in the Kv7.1-encoding gene KCNQ1 account for ~40% of long QT syndromes with known genetic basis (LQT1)." (PMID 28959214, 2017). "The population also contain individuals with the Swedish long QT syndrome (LQTS1) founder mutation (KCNQ1/p.Y111C) which in homozygotes causes the Jervell & Lange Nielsen syndrome (JLNS) and hearing loss (HL)." (PMID 29270100, 2017). "The first heart channelopathy to be discovered was a congenital form of long QT syndrome (LQT1) due to mutations in KCNQ1 encoding the main subunit (Kv7.1) of the K channel responsible for the slow delayed rectifier current (IKs) in cardiomyocytes." (PMID 27242528, 2016). "Congenital long QT syndrome (LQTS) is due to direct mutations in specific genes such as the cardiac delayed rectifier potassium channel (KCNQ1 and KCNH2) or the cardiac sodium channel (SCN5A)." (PMID 27301406, 2016). "They studied the long QT syndrome-associated mutations R539W and R555C, located within helix C of the C-terminus, and found that these mutations decrease the apparent affinity KCNQ1+KCNE1 channels to exogenous PIP2." (PMID 24904429, 2014). "Lopes and colleagues found that the long QT syndrome-associated mutation R366Q increased the sensitivity of KCNQ1+KCNE1 channels to PIP2 hydrolysis." (PMID 24904429, 2014). "In the case of KCNQ1, loss of interaction between AKAP9 and KCNQ1 leads to a potentially fatal heart condition, long-QT syndrome, which also arises in cases with loss of function mutations in KCNQ1 itself." (PMID 24467814, 2014). "KCNQ1 is expressed in cardiomyocytes, where its abnormal trafficking was linked to hereditary long QT syndrome." (PMID 24037260, 2013). "Non-synonymous variant rs12720449 (P448R), located in exon 10 of KCNQ1, was also found to be associated with Long-QT syndrome." (PMID 22479571, 2012). "Mutations of KCNQ1 genes that result in reduction or loss of channel activity cause prolongation of repolarization during action potential, thereby causing long QT syndrome (LQTs)." (PMID 23251633, 2012). "Variants of the pore-forming alpha-subunit potassium channel gene KCNQ1 are associated with reduced insulin secretion and T2D, and with forms of the long QT-syndrome." (PMID 21291537, 2011).
long QT syndrome (continued). "Mutations of KCNQ1 cause a number of life threatening diseases, for instance, loss of function mutations cause the common cardiac arrhythmia Long QT syndrome associated with increased risk of Torsades des Pointes arrhythmia and sudden death." (PMID 21915266, 2011). "KCNQ1 is imprinted at the majority of expressed sites in the human, except in the heart, the site of the defect in long-QT syndrome that are caused by mutations in KCNQ1." (PMID 20617174, 2010). "Mutations in HERG and KCNQ1 potassium channels have been associated with Long QT syndrome and atrial fibrillation, and more recently with sudden infant death syndrome and sudden unexplained death." (PMID 18590565, 2008). "Interestingly, a similar phenomenon is observed in KCNQ1-D242N mutations found in patients with long QT syndrome." (PMID 39971736, 2025). "The KCNQ1 gene is the closest to rs2074238 at 18,889 bp; its gene product is a potassium voltage gated channel with alleles responsible for hereditary forms of long QT syndrome." (PMID 39774334, 2025). "Long QT syndrome is primarly associated with KCNQ1, KCNH2, and SCN5A gene mutations." (PMID 41590224, 2025). "The alteration of hERG trafficking, caused by the KCNQ1 variant, leads to HF and long QT syndrome." (PMID 38420267, 2024). "KCNQ1 (then named KVLQT1) gene was first reported as a causative gene of long QT syndrome." (PMID 38503563, 2024). "Among these candidates, Kcnq1 stands out for its prior association with long QT syndrome." (PMID 36454649, 2023). "KCNQ1 causes Long-QT syndrome (OMIM #192500) and other types of cardiac arrhythmias." (PMID 37065762, 2023). "KCNQ1 (Kv7.1) dysfunction causes long QT syndrome progression." (PMID 36012639, 2022). "KCNQ1 (potassium voltage-gated channel subfamily Q Member 1) is implicated in long QT syndrome (LQTS) and cardiac arrhythmia, while its significance in LUAD remains unclear." (PMID 35216393, 2022). "In addition, mutations in cardiac KCNQ1 channels account for the most common congenital defects that cause long QT syndrome (LQTS), which is a heart disorder resulting in cardiac arrhythmias and about 3000 sudden deaths." (PMID 35216393, 2022). "Autosomal dominant mutation in KCNQ1 causes congenital long-QT syndrome and cardiac arrhythmia." (PMID 33484326, 2021). "Moreover, as cardiac channelopathies, mainly represented by long QT syndrome, are cardiac defects predisposing to sudden death, in further investigations, the role of KCNQ1, KCNH2, and SCN5A genes should be excluded." (PMID 33815256, 2021). "Increased sympathetic tone during the early stage of HUTT may induce macroscopic TWA in long QT syndrome with KCNQ1 gene mutation." (PMID 32443288, 2020). "The underlying genetic defects of long QT syndrome were first described in the 1990s, identifying three genes (KCNQ1, KCNH2, and SCN5A) that encoded ion channel proteins (KvLQT1, hERG, and NaV 1.5) responsible for transmembrane ion currents critical to cardiac depolarization and repolarization." (PMID 32494476, 2018). "Variants in the KCNQ1 gene can cause two hereditary variants of congenital long-QT syndrome (LQTS)." (PMID 28595573, 2017). "There are reports that the mutant KCNQ1 is implicated in various cardiac dysfunctions caused by lipid metabolism, familial atrial fibrillation, and long QT syndrome." (PMID 28863213, 2017). "Mutations in the KCNQ1 gene were associated with a particular form of long QT syndrome, the LQT1." (PMID 27064559, 2016). "We speculate that this PIP2-independent tryptophan-cholesterol interaction is responsible for the difference in phenotypes observed for patients with long QT syndrome caused by R539W and R555C mutations of KCNQ1." (PMID 24681627, 2014).
long QT syndrome (continued). "Mutations in KCNQ1(Kv7.1) are responsible for one form of long QT syndrome (LQT1)." (PMID 24062639, 2013). "Mutations in KCNQ1 cause long QT syndrome and familial atrial fibrillation." (PMID 20174558, 2010). "Moreover, the T160M polymorphism of TRPM4 (together with the G219E of KCNQ1) was found in a family where carriers experienced long QT syndrome, which might implicate the role of TRPM4 in the maintenance of normal AP duration." (PMID 34502410, 2021). "This may further increase the susceptibility for cardiac events in KCNQ1 long QT syndrome patients." (PMID 29259974, 2017). "Furthermore, patients with loss-of-function mutations in KCNQ1 and long QT syndrome may have an additional risk for cardiac events due to development of hyperinsulinemia with subsequent hypoglycemia and hypokalemia." (PMID 29259974, 2017). "However, several mutations in KCNQ1 leading to a “long QT syndrome” of cardiac arrhythmias (Y111C, L114P, and P117L) or Benign Familial Neonatal Seizures (R353G and L339R) mutations in KCNQ2 reduced channel expression via effects on trafficking of the channels." (PMID 26692086, 2015). "Since Kcnq1 is associated with long QT syndrome, it will be interesting to determine whether there are mutations in the non-coding portions of the gene that could be responsible for the cardiac phenotypes that have not been associated with mutations in the protein-coding regions." (PMID 25539921, 2015). "The proband (II-2) with Long QT syndrome (LQTS), isolated ventricular fibrillation, and an ICD implant carries the pathogenic KCNQ1 variant c.1343del (p.Pro448GlnfsTer18)." (PMID 41287789, 2025). "Susceptibility genes can be analyzed, such as KCNQ1, KCNH2, KCNE1, and KCNE2, which are involved in long QT syndrome, the RYR2 gene implicated in catecholaminergic polymorphic ventricular tachycardia type 1, or the SCN5A gene associated with Brugada syndrome." (PMID 40361926, 2025). "Loss-of-function mutations in KCNQ1 and KCNE1 cause long QT syndrome (LQTS) types 1 and 5 (LQT1/LQT5), accounting for over one-third of clinical LQTS cases." (PMID 41034624, 2025). "Next is the potassium voltage-gated channel KQT-like member 1 (KCNQ1), whose activation effects include long QT syndrome, potential hearing impairment, deafness, and gastrointestinal symptoms." (PMID 41471088, 2025). "Several genes, especially channelopathies, have been identified in patients who died of SUDEP including gene variants associated with seizures (e.g., SCN1A, SCN8A, SCN2A) or long QT-Syndrome (SCN5A, KCNH2, KCNQ1)." (PMID 40703772, 2025). "Similar findings as in KCNQ1-related Long-QT syndrome were made in patients with mutations in KCNH2, the second most common cause of Long-QT syndrome (OMIM #613688)." (PMID 37065762, 2023). "There was an excess burden of splice-disrupting variants in PKP2 (5.9%), FLNC (2.7%), TTN (2.8%), MYBPC3 (8.2%) and MYH7 (1.3%), in distinct cardiomyopathy subtypes, and KCNQ1 (3.6%) in long QT syndrome." (PMID 37821546, 2023). "He had a well-recognised variant in KCNQ1, p.(Arg192fs) (ClinVar, VCV000053072.23), a gene known to be associated with long QT syndrome that was included in the ACMG list of 56 genes recommended for screening." (PMID 37946251, 2023). "Two patients with secondary findings in FBN1 and KCNQ1 were confirmed to have previously unidentified Marfan and long QT syndromes, respectively, and were referred for further clinical interventions." (PMID 37946251, 2023). "For instance, KCNQ1 (Long QT syndrome type 1, MIM 192500) and SCN5A (Long QT syndrome 3/Brugada syndrome MIM 603830/601144) have been associated with Long QT syndrome and sudden death." (PMID 36143288, 2022). "These include rodents with mutations in the SCN1A gene (mimics Dravet syndrome), SCN5A gene (mimics Brugada syndrome), KCNH2, KCNQ1 genes (mimics Long QT syndrome), etc.." (PMID 35754505, 2022).
long QT syndrome (continued). "The LVNC caused by RYR2, KCNQ1, and KCNH2 mutations occurred with catecholamine-sensitive VT, long QT syndrome (LQTs), torsade de pointes, and ventricular fibrillation." (PMID 34819141, 2021). "In the context of therapy of the long QT syndrome, activation of KCNQ1/KCNE1 channels was discussed as a therapy option." (PMID 32338831, 2020). "Impaired function of the voltage-gated potassium channels Kv7.1 (encoded by KCNQ1) and Kv11.1 (encoded by KCNH2), caused by inheritable mutations or drugs leads to long QT syndrome (LQTS) characterised by malignant cardiac arrhythmias." (PMID 32164657, 2020). "CNVs involving single or multiple exons of the major channelopathy genes, KCNQ1, KCNH2, SCN5A, and RYR2, uncommonly serve as the pathogenic basis of dominantly inherited arrhythmia syndromes such as long QT syndrome, Brugada syndrome, and CPVT." (PMID 32663189, 2020). "Hundreds of mutations in the genes (KCNQ1 and KCNE1) encoding the IKs channel cause long QT syndrome (LQTS)." (PMID 33322401, 2020). "Mutations in the KCNQ1 and KCNE1 interface cause long QT syndrome and atrial fibrillation which results in prolongation of the QT interval of heart repolarization." (PMID 31941450, 2020). "The KCNQ1 gene has a significant role in long QT syndrome, Jervell and Lange-Nielsen syndrome, familial atrial fibrillation, and short QT syndrome." (PMID 30866607, 2019). "ML277 provides insights and a tool to investigate the gating mechanism of KCNQ1 channels, and our study reveals a new strategy for treating long QT syndrome by specifically enhancing the AO state of native IKs currents." (PMID 31329101, 2019). "Genetic variants in KCNQ1 and CDKL5 genes were identified in ID#1, who had family members affected by epilepsy and/or long QT syndrome." (PMID 29261713, 2017). "Defects in KCNQ1 are responsible for congenital long-QT syndrome, with cardiac phenotypes of different severities." (PMID 25539921, 2015). "However, non-penetrance is not restricted to the mutations we described, but is, rather, a common feature in most, if not all, of the described genes that may cause CHD in humans such as PTPN11 in Noonan Syndrome, KCNQ1 in Long QT Syndrome and troponin T in Familial Hypertrophic Cardiomyopathy." (PMID 19886994, 2009). "KCNQ1 and KCNH2 are the two most common potassium channel genes causing long QT syndrome (LQTS), an inherited cardiac arrhythmia featured by QT prolongation and increased risks of developing torsade de pointes and sudden death." (PMID 18808722, 2008). "Mutations that disrupt normal biosynthesis and function of KCNQ1 and HERG have been associated with three cardiac arrhythmias: Short QT syndrome (SQTS), atrial fibrillation and Long QT syndrome (LQTS)." (PMID 18590565, 2008). "In addition, the same research group identified other genetic mutations associated with Long QT Syndrome (LQTS) in 3 of 58 (5.2%, 2 SCN5A and 1 KCNH2) white infants and 1 of 34 (2.9%, 1 KCNQ1) black infants." (PMID 41062843, 2026). "In this context, susceptibility genes can be analyzed, such as KCNQ1, KCNH2, KCNE1, and KCNE2, which are involved in long QT syndrome, the RYR2 gene implicated in catecholaminergic polymorphic ventricular tachycardia type 1, or the SCN5A gene associated with Brugada syndrome." (PMID 40361926, 2025). "It is now known that mutations in Kv genes (KCNQ1–5) are related to several disorders like long-QT syndromes (KCNQ1) and a range of neuropsychiatric disorders (KCNQ2–5), ranging from some types of neonatal epilepsy (NEE) and epileptic encephalopathies (DEEs) up to developmental disorders." (PMID 38999185, 2024). "pointed out that patients with KCNQ1-related Long-QT syndrome may exhibit hyperinsulinemia and symptomatic reactive hypoglycemia after glucose challenge." (PMID 37065762, 2023).
long QT syndrome (continued). "SCN5A (p.R661W, p.R965C and p.A1374S) and KCNH2 (p.R692Q) may cause Brugada syndrome, while SCN5A (p.R1880H), KCNQ1 (c.922-1G > C and p.R243S) and KCNH2 (p.D161N and p.A188Gfs*143) may lead to long QT syndrome." (PMID 36303204, 2022). "The mother has long‐QT syndrome, caused by a known pathogenic variant in KCNQ1 (NM_181798.1: c.1385G>A:p.G462D) (# 192500); not present in her son) but is otherwise healthy." (PMID 33982443, 2021). "Women have a higher predisposition to genetic mutations that potentiate TdP and have a higher risk of TdP with Long QT syndrome (LQTS) type 1 and type 2, caused by mutations in potassium channel gene KCNQ1 (KvLQT1) and mutations in potassium channel gene KCNH2 (also known as hERG), respectively." (PMID 33102533, 2020). "Inheritance of GHD in our families, however, followed an autosomal dominant pattern, and similarly, a lack of a parent-of-origin effect has been described in the long QT syndrome caused by loss-of-function KCNQ1 mutations." (PMID 29097701, 2017). "Moreover, novel associations between three genes (KCNQ1, KCNH2, and KCNE2) associated with Long QT syndrome and HCM phenotype were proposed." (PMID 28750076, 2017). "Mutations in either KCNQ1 or KCNE1, with a subsequent reduction of the current, may lead to congenital long QT syndrome." (PMID 29259974, 2017). "KCNQ1, the potassium voltage-gated channel, is an example of a gene that causes two clinically distinct conditions: Jervell and Lange-Nielsen Syndrome (JNLS), and long QT syndrome (LQTS)." (PMID 27446933, 2016). "For comparison, in long-QT syndrome the rate of “mutations” without clinical phenotype in the three most frequently involved genes KCNQ1, KCNH2, and SCN5A is only 5 %." (PMID 26701096, 2015). "The mother and the brother of the index case were also affected by Long QT Syndrome, and family cosegregation was observed for the KCNQ1 deletion, but not for the TTN variant." (PMID 25494010, 2014). "Variable imprinting of the KCNQ1 gene provides a possible explanation for the existence of long QT syndrome (LQTS) in the absence of a coding sequence mutation in KCNQ1." (PMID 24198825, 2013). "KCNQ1 is a major target of anti-arrhythmic drugs, with blockers prolonging repolarization hence treating Short QT syndrome and openers speeding repolarization in Long QT syndrome." (PMID 21915266, 2011). "Only three genes, namely KCNQ1, KCNH2, and SCN5A, were systematically documented as definitive contributors to typical long QT syndrome (LQTS), with each gene corresponding to major forms of LQTS denoted as LQT1, LQT2, and LQT3, respectively." (PMID 38339103, 2024). "The discovery of cardiac ion channel genes underpinning Long QT Syndrome (LQTS; MIM 192500) in the 1990s–KCNQ1 (KVLQT1), KCNH2 (KV11.1/hERG), SCN5A (NaV1.5) —were a major breakthrough in our understanding of congenital arrhythmia syndromes." (PMID 38089476, 2023). "However, subsequent examination of post-mortem samples found that the boy who died had cardiac features inconsistent with long QT syndrome, did not have the KCNQ1 variant found in the wider family, and instead had a clearly disease-causing de novo variant in DES, a gene linked to cardiomyopathy." (PMID 30837331, 2019). "The aim of the present study was to analyze the relationship of KCNQ1 and KCNH2 expression level with the occurrence of the long-QT syndrome." (PMID 23936797, 2013). "The potassium voltage-gated channel, KQT-like subfamily member 1 (KCNQ1) is a member of 11 mammalian Kv channel families and has been extensively studied for its role in long QT syndrome." (PMID 21261977, 2011). "Kv7.1 is located in both cardiomyocytes and pancreatic β-cells, and it was hypothesized that patients with KCNQ1 long QT syndrome may exhibit increased insulin secretion." (PMID 29259974, 2017).